NPC1 (NPC intracellular cholesterol transporter 1)
Diseases named in the same sentence as NPC1 in open-access papers (continued):
Sharing a sentence is not in itself a finding about the gene and the disease.
infection (continued). "The essential nature of NPC1 for infection in cells derived from mammals of multiple species, including bats, and for infection and in vivo pathogenesis in lethal EBOV infection mouse models argues against the existence of alternative filovirus entry receptors." (PMID 26698106, 2015). "Interestingly, the results in lane 8 show a striking decrease in NPC1 expression upon infection of one of the NPC2D cell lines with HIV-1." (PMID 22273177, 2012). "Thus, viruses such as Ebola and Marburg require NPC1 protein expression for productive infection and the second luminal domain of NPC1 binds directly and specifically to the GP1 viral glycoprotein." (PMID 23153210, 2012). "Moreover, it has been shown that the chemical substance U18666A may block NPC1 activity, hence reducing infection with numerous flaviviruses, including ZIKV, WNV, YFV, and DENV." (PMID 38098077, 2023). "In addition, inhibition of NPC1 function by the chemical compound U18666A, was also shown to inhibit the infection of Chikungunya, an alphavirus and, several flaviviruses such as Zika Virus (ZIKV), West Nile Virus (WNV), Yellow Fever Virus (YFV) and Dengue Virus (DENV)." (PMID 35081156, 2022). "Thus, exploring how NPC1 sequences relates to infection status in bats may improve prediction, especially given the low sensitivity of the alternative TP model." (PMID 36542657, 2022). "However, the transcriptional expression of venom apolipophorin-like protein 1 and NPC1 lipid transporters was lower upon infection, which may impair the storage of this reserve to the vector." (PMID 34988032, 2021). "A. phagocytophilum obtains cholesterol exclusively by hijacking the Niemann–Pick type C protein 1 (NPC1) pathway that mediates lysosomal cholesterol efflux, which makes it an ideal organism for evaluating the efficacy of FIASMAs for inhibiting infection by an LDL cholesterol–dependent pathogen." (PMID 30902833, 2019). "However, it should be noted that infection with some enveloped viruses from Rhabdoviridae [vesicular stomatitis virus] or Orthomyxoviridae [infiuenza A virus] occurs independently of NPC1." (PMID 31866985, 2019). "We also found that NPC1 could influence the cellular host range of filoviruses—human NPC1 conferred susceptibility to filovirus entry and infection when expressed in the nonpermissive reptilian cell line VH-2, derived from a Russell’s viper (Daboia russellii)." (PMID 27303731, 2016). "Alternatively, it is conceivable that repeated contacts between unknown (non-bat) reservoir hosts carrying specific filoviruses, and bats of particular species, have driven positive selection in bat NPC1 to limit infection (and selection of filoviruses with compensating sequence changes in GP)." (PMID 26698106, 2015). "In this study, we show that inhibition of the cholesterol transporter activity of NPC1 in cells that express both ACE2 and TMPRSS2, considerably reduces SARS-CoV-2 infectivity, evaluated as early as 4 h post-infection." (PMID 39707537, 2024). "To ascertain if NPC1 knockdown impeded the entry phase of the pseudoviral life cycle in a manner comparable to what we saw upon NPC1 inactivation, we quantified the fraction of GFP-positive cells 4 h after infection, instead of 24 h later." (PMID 39707537, 2024). "NPC1 inhibition in Calu-3 and VERO-76 cells produced similar patterns of resistance to VSV-Spike-GFP infection and propagation." (PMID 39707537, 2024). "Further, it was demonstrated that the carbazole SC816 and the sulfides SC198 and SC073, all of which were known to interact with NPC1, were effective in inhibiting SARS-CoV-2 infection in human cell infection models with a high selectivity index." (PMID 38098077, 2023). "Deletions of NPC1, CCZ1 and RAB7 lead to a marked decrease in VSVΔG/MARVGP infection as determined by a decrease in VSV-M protein." (PMID 37880247, 2023). "As NPC1 acts as an intracellular receptor for EBOV, NPC1 KO cells should be resistant to infection with this virus as previously reported." (PMID 35081156, 2022).
infection (continued). "We identified NPC1 in CRISPR and RNA interference screens as a putative host factor for infection by mammalian orthoreovirus (reovirus)." (PMID 35263388, 2022). "An example is Ebola virus (EBOV), in which NPC1 has a pivotal role at infection, given that the EBOV Glycoprotein (GP) interacts with NPC1 to achieve endosomal fusion and cytoplasmic penetration." (PMID 35081156, 2022). "A. phagocytophilum captures cholesterol exclusively from LDL, and NPC1 and FLOT2 both target A. phagocytophilum inclusions and are required for infection." (PMID 34544283, 2021). "Apilimod and Vacuolin-1 also prevented entry and infection of VSV-MeGFP-ZEBOV and many of the internalized VSV-MeGFP-ZEBOV virions colocalized with NPC1 in the distended, vacuolated endosomes." (PMID 32764148, 2020). "In contrast, the percent infection with the H5-S-FLU virus was the same for wild-type and NPC1-KO cells." (PMID 29212933, 2018). "The essential role of NPC1 in EBOV entry and infection was powerfully illuminated in a haploid genetic screen." (PMID 28403145, 2017). "Our hypothesis that NPC1 in bats has been genetically sculpted by filoviruses (and vice versa) presupposes not only a long-term coevolutionary relationship, but also one in which these viruses have imposed selective pressure on bats to limit or eliminate infection." (PMID 26698106, 2015). "Next, using the pseudovirus system, the authors confirmed that NPC1 is essential for DEHV entry, as cells lacking NPC1 did not support infection, thus validating previous findings." (PMID 40728408, 2025). "We also found that the infection of SARS-CoV-2 VOCs, SARS-CoV, and MERS-CoV are dependent on NPC1." (PMID 38167417, 2024). "Therefore, in cases of infection by viruses such as EBOV, the human intracellular cholesterol transporter 1 (NPC1), which is present mainly in syncytiotrophoblasts in the placenta, is crucial for this virus to enter the cell and cause an infection." (PMID 38534983, 2024). "Disrupting the NPC1/EBOV-GP interaction may be an attractive strategy for the development of drugs intended to stop viral entry and the ensuing infection." (PMID 38098077, 2023). "NPC1 shRNA, Lamp2 shRNA and scrambled (SCR) shRNA Vero cells were infected with recombinant fluorescent virus (B54GFP), which expresses GFP as a fusion of the major infection protein p54, at a MOI 1 pfu/ml to infect cells." (PMID 35081156, 2022). "Therefore, we set out to investigate the potential interaction of the E248R and E199L proteins of ASFV with one of the endosomal protein responsible for cholesterol trafficking, NPC1, and also its possible role in ASFV infection." (PMID 35081156, 2022). "Absence of NPC1 did not dampen infection by infectious subvirion particles, which are reovirus disassembly intermediates that bypass the endocytic pathway for infection of target cells." (PMID 35263388, 2022). "Niemann-Pick C1 (NPC1), a lysosomal cholesterol transporter, was verified to be essential for efficient infection of eHEV, as depletion of NPC1 reduced eHEV but not HEV infectivity in hepatocytes." (PMID 34578238, 2021). "The successful VSV-MeGFP-ZEBOV infection observed in the absence of drug in cells expressing NPC1-Halo alone or in combination with mScarlet-EEA1 indicates that NPC1-Halo is capable of facilitating infection and that VSV-MeGFP-ZEBOV trafficked to NPC1-Halo−containing endosomes." (PMID 32764148, 2020). "We surmised that the filovirus receptor, NPC1, might explain the selective resistance of the African straw-colored fruit bat cells to EBOV entry and infection." (PMID 26698106, 2015). "Unexpectedly, no infection-driven changes on NPC1 on the transcriptional level were noted." (PMID 39183751, 2024). "We have reported new data on the altered endosomal exit of ASFV in the absence of NPC1, as we were able to identify incoming viral cores could retained inside endosomes, preventing them from continuing infection." (PMID 35081156, 2022).
infection (continued). "This was verified by infection with a vesicular stomatitis virus (VSV) pseudotyped with the glycoprotein (GP) of the Mayinga strain of EBOV, confirming the functional abrogation of NPC1 in these KO cells S8E Fig)." (PMID 35081156, 2022). "As such, our hypothesis is that VSV-EBO GP (GFP) cannot launch infection because particles containing cleaved GP do not reach NPC1 positive compartments." (PMID 35320319, 2022). "Whether NPC1 can predict the likelihood of infection in the wild for species sampled for ebolaviruses has not been tested." (PMID 36542657, 2022). "Because NPC1 and FLOT2 are required for A. phagocytophilum infection and we found that ezetimibe blocks NPC1-FLOT2 colocalization and interaction, we examined whether ezetimibe could block infection of cells with A. phagocytophilum." (PMID 34544283, 2021). "Interestingly, infection studies in A549 cell lines shows IFITM3 has greater antiviral activity against IAV and SARS-CoV-2 infection, whereas IFITM2 is more active against EBOV, that enter host cells through interactions with NPC1 in late endosomes." (PMID 34981045, 2021). "While we did not observe differences in NPC1 mRNA expression between infected and uninfected monocytes, expression of known EBOV entry factors like cathepsin B and L were associated with infection." (PMID 33159858, 2020). "More recently, NPC1 has been shown to act as an invasion receptor for Ebola and Marburg viruses, suggesting a direct role for NPC1, possibly independent of cholesterol trafficking in the infection of filoviridae." (PMID 23094108, 2012). "However, the antiviral compounds that interact with NPC1, such as carbazole SC816 and sulfides SC073 and SC198 (drugs used to elucidate the interaction between EBOV-GP and NPC1) can reduce SARS-CoV-2 infection with a good selectivity index in human cell infection models." (PMID 34975904, 2021). "Nevertheless, our finding that two snake NPC1 orthologs are nonpermissive to filovirus entry and infection due to a single amino acid change leads us to speculate that this change was an adaptation to reduce infection by a filovirus, thereby increasing host survivability." (PMID 27303731, 2016). "After analysing the impact of the absence of NPC1 in ASFV entry, we also tested its impact in later stages of infection." (PMID 35081156, 2022). "After confirming the interaction of viral proteins with NPC1, and to study the possible role of NPC1 in ASFV infection, we tested the impact of the absence of this cellular protein on the infection." (PMID 35081156, 2022). "For instance, TIM1 was unable to enhance the infection of EBOV and MARV pseudoviruses in the absence of the intracellular filovirus entry factor NPC1." (PMID 23555248, 2013). "Finally, siRNA-mediated KD of NPC-1 in PEC (due to failure of successful KD generation in KCs), resulted in significant increase in amastigote load in response to LD-R-infection, while no such change in amastigote load was observed for LD-S-infected NPC-1-KD-PECs (Figure 6Gi–iv)." (PMID 40424189, 2025).
neurodegenerative disease (31 papers, 2011 to 2025). A disorder of the central nervous system characterized by gradual and progressive loss of neural tissue and neurologic function. "Niemann-Pick type C1 (NP-C1) is a fatal, progressive neurodegenerative disease caused by mutations in the NPC1 gene." (PMID 35159129, 2022). "Niemann–Pick C1 disease (NPC1) is a rare, fatal neurodegenerative disease caused by mutations in NPC1, which encodes the lysosomal cholesterol transport protein NPC1." (PMID 34407999, 2021). "Patients with a NPC1I1061T mutation develop NPC1 neurodegenerative disease, raising two questions: is the mechanism described herein conserved in neurons and, if so, what are the implications of altered neuronal SOCE for NPC disease?" (PMID 31601621, 2019). "Niemann-Pick C1 (NPC1) is a Mendelian disorder caused by >300 variants in the NPC1 gene that disrupt cholesterol homeostasis leading to the rapid onset and progression of neurodegenerative disease." (PMID 31699992, 2019). "Findings from animal models highlight that heterozygous NPC1 mutations affect neuronal function and neurodegenerative disease status, particularly in the context of aging." (PMID 24386122, 2013). "NPC1 is a rare progressive neurodegenerative disease caused by mutations in the NPC1 gene located on chromosome 18q11 encoding for a 1278-amino acid intracellular membrane glycoprotein." (PMID 24044630, 2013). "Under basal conditions, the three NPC1-deficient cell lines showed an increased LC3BII/LC3BI ratio, which was in accordance with previous findings in NPC1-deficient cells and other neurodegenerative diseases, pointing at a defective clearance of autophagic vesicles." (PMID 35159316, 2022). "NPC1, like other neurodegenerative diseases, is characterized by the selective loss of neurons." (PMID 33445799, 2021). "The approval was based on reduced plasma NfL levels associated with treatment, laying the framework for the possible use of NfL as a readout measure for clinical trials of NPC1 and other neurodegenerative diseases." (PMID 40821948, 2025). "Among the top 50 proteins showing increased expression, ranked by fold-change, several proteins identified in the PEA screen of NPC1 CSF have been identified in other neurodegenerative diseases." (PMID 36721240, 2023). "Pathway analysis of differentially expressed genes showed similarities in microglia activation between NPC1 and common neurodegenerative diseases." (PMID 32731618, 2020). "OS is a common pathophysiological feature in neurodegenerative diseases and has also been described for NPC1." (PMID 33081384, 2020). "Increased levels of ROS and associated changes in cellular pathways and functions contribute crucially to the pathology of neurodegenerative diseases such as NPC1." (PMID 33081384, 2020). "The results presented in this paper for MLIV microglia, along with our prior characterization of NPC1 microglia, suggest that microglia from common and rare neurodegenerative diseases share similarities in their activation pattern." (PMID 31883529, 2019). "Impaired olfaction, known to occur in many neurodegenerative diseases, may also constitute a key symptom in Npc1." (PMID 39081805, 2024). "This strategy may be applicable to the treatment of several neurodegenerative diseases (including NPC1) through the elimination of harmful circulating monocytes." (PMID 37369603, 2023). "A recent study has suggested that ventricular volume may affect CSF protein concentration, thus this may need to be considered as a potential confounder in neurodegenerative diseases such as NPC1." (PMID 36721240, 2023). "Additionally, in a mouse model, genetic inactivation of ACAT1/SOAT1 was recently shown to benefit a rare pediatric neurodegenerative disease, Niemann-Pick type C1 (NPC1)." (PMID 36982602, 2023). "Iba1, a marker of microglia that is associated with inflammatory processes in neurodegenerative diseases, revealed no reactivity in OB of sham-treated NPC1+/+ mice." (PMID 30154701, 2018).
neurodegenerative disease (continued). "The NPC1 disease animal models, combined with cell- or tissue-specific rescue experiments, might be useful for comparing and contrasting neurodegenerative disease pathways in order to discover universal or distinct mechanisms." (PMID 23907005, 2013). "Initial increases in oxidative stress or initial metabolic alterations can thus cause further changes in energy metabolism and increase oxidative damage in Npc1-/- brain, leading to a cascade of subsequent adaptations as seen in many neurodegenerative diseases." (PMID 24367541, 2013). "Given reports that ER Ca2+ pathways are dysregulated across several neurodegenerative diseases and the correlation between altered cholesterol homeostasis and neurodegeneration, we hypothesized that the aberrant cholesterol efflux in NPC1 disease may perturb ER Ca2+ signaling pathways." (PMID 31601621, 2019). "However, as part of a combined therapy, inhibition of necroptosis in NPC1 may contribute significantly to the treatment of this progressive neurodegenerative disease." (PMID 26986514, 2016). "In the further development of CD-based therapy for individuals with cardiovascular and neurodegenerative diseases, a major key issue may be the unwanted side effects as reported for HPβCD in the cat model of NPC1, and that is actually in clinical trials for NPC1." (PMID 27999408, 2016). "Comparison of transcriptomes shows similarities between neurodegenerative disease, AD, aging, ALS, MLIV, and NPC1." (PMID 31883529, 2019). "Olfactory impairment influences the patient’s quality of life in an increasingly aging society, but investigations on the significance of olfactory dysfunction in neurodegenerative diseases, such as Niemann–Pick type C1 (NPC1), is usually not in the focus of research." (PMID 30154701, 2018).